STAT3 (signal transducer and activator of transcription 3)
Diseases named in the same sentence as STAT3 in open-access papers (continued):
Sharing a sentence is not in itself a finding about the gene and the disease.
Insulin resistance (171 papers, 2005 to 2026). Increased resistance towards insulin, that is, diminished effectiveness of insulin in reducing blood glucose levels. "The protection of mice with a macrophage-specific Stat3 deficiency against insulin resistance is associated with the reduced tissue infiltration by macrophages." (PMID 40801626, 2025). "Pathways linked to TNF-α and IL-6/JAK/STAT3 signaling are well-established contributors to adipose inflammation and systemic insulin resistance." (PMID 41148235, 2025). "Among adipocytokines, leptin is associated with insulin resistance via shared signaling pathways—such as JAK2/STAT3, MAPK, and PI3K—with insulin in the placenta." (PMID 40725173, 2025). "Chronic overexpression of SOCS3, a direct STAT3 target, has been implicated in leptin and insulin resistance, highlighting the importance of tightly regulated STAT3 activity for metabolic homeostasis." (PMID 40704145, 2025). "It has also been suggested that SEA binds to the cytokine receptor gp130 and activates signal transducer and activator of transcription 3 (STAT3), which induces chronic inflammation and potentially causes insulin resistance." (PMID 37110462, 2023). "The reduced phosphorylation of JAK2 and STAT3 in LEPTIN deficient pig livers led to hepatic insulin resistance and increased fat synthesis marked by activation of SOCS3 and SREBP-1c, respectively, further confirms the value of the pig model." (PMID 37705071, 2023). "Remarkably, MK hindered the insulin-stimulated translocation of the glucose transporter GLUT4 to the surface of adipocytes and activated the STAT3-suppressor of cytokine signaling 3 pathway, implicated in adipocyte insulin resistance." (PMID 36204583, 2022). "Several studies have demonstrated that hepatocyte-specific deficiency of STAT3 can lead to insulin resistance and increased expression of gluconeogenic genes via the disruption of interleukin-6 (IL-6) signalling." (PMID 35896788, 2022). "The participation of mTOR in the SOSC3/STAT3 pathway, induced by IL-6, can intensify insulin resistance, causing the development of related pathological disorders, such as T2DM and GDM." (PMID 35052633, 2022). "STAT3 (Signal Transducer And Activator Of Transcription 3) activation has been informed to be implicated in the progression of diabetic insulin resistance by regulating set genes involved in glycolipid metabolism and insulin sensitivity." (PMID 35956419, 2022). "Complementary to this, hepatocyte-specific IL6R, IL6, or STAT3 deficient mice develop increased gluconeogenesis and insulin resistance, as a result of G6pc upregulation, likely via a PI3K/FoxO1-independent pathway, as well as age-related obesity and steatosis." (PMID 30374109, 2018). "Chronic IL-6-mediated activation of signal transducer and activator of transcription 3 (STAT3) can cause hepatic insulin resistance critical for the development of glucose intolerance and steatotic HCC10,11." (PMID 30523261, 2018). "STAT3, which is downstream of IL-6 signaling, is reported to be associated with IL-6-induced insulin resistance and gluconeogenesis in the liver and muscle." (PMID 28706484, 2017). "STAT3 is implicated in development of IL-6-induced insulin resistance in cultured skeletal myotubes obtained from patients with impaired glucose tolerance." (PMID 28706484, 2017). "Mice with liver-specific knockout of STAT3 display insulin resistance associated with increased expression of hepatic gluconeogenic genes, such as PEPCK-C and G6Pase." (PMID 24586865, 2014). "We hypothesized that EPO ameliorates insulin resistance and associated vascular/renal inflammation via STAT3 activation." (PMID 40943240, 2025). "Furthermore, the protection of obese mice with myeloid-specific Stat3 deficiency against insulin resistance is also associated with reduced tissue infiltration by macrophages." (PMID 40801626, 2025).
Insulin resistance (continued). "Intriguingly, these effects were (partially) blocked with metformin, suggesting that insulin resistance is causative, and by the inhibition of the signal transducer and activator of transcription 3 (STAT3) signaling pathway, which is largely activated by leptin." (PMID 38470692, 2024). "Interestingly, the activation or loss of STAT3 can lead to insulin resistance, the loss of muscle mass, or the increased repair of MuSCs depending on the stimuli and the duration of STAT3 depletion." (PMID 35902482, 2023). "Likewise, constitutive STAT3 phosphorylation is linked to the development of insulin resistance in skeletal muscle." (PMID 35884769, 2022). "STAT3 is associated with IL-6-induced insulin resistance in human skeletal muscle." (PMID 36159557, 2022). "However, the studies of STAT3 gene polymorphism, insulin resistance, and type 2 diabetes are comparatively insufficient." (PMID 33833859, 2021). "While JAK2 and STAT3 were associated with all the noted pathways except insulin resistance and Herpes simplex infection, respectively, only two connections (negative regulation of cell proliferation and insulin resistance) were reported for NOS3." (PMID 33100263, 2020). "Next, we investigated whether the visfatin-induced increases in STAT3 and NF-κB activities were associated with insulin resistance." (PMID 31396538, 2019). "The Con-Can mice in this study showed higher body weight gain and insulin resistance, two important features of metabolic syndrome and risk factors for systemic and chronic inflammation; therefore, we examined the protein expression of NF-κB, STAT3, VCAM, NLRP3, and IL-1β in peritumor tissues." (PMID 34876963, 2021). "We show through both Mx-1 Cre mice and CpG-Stat3 siRNA that blocking Stat3 in B and myeloid cells can effectively reduce insulin resistance." (PMID 40801626, 2025). "Mechanistically, JAK2 overexpression amplifies the insulin promoter activity, whereas phosphorylated STAT3 impairs the insulin signaling and glucose uptake in skeletal muscle, driving insulin resistance." (PMID 40831950, 2025). "In PCOS studies, troxerutin troxerutin has been shown to attenuate dihydrotestosterone-induced insulin resistance in rats by inhibiting IL-22/JAK1/STAT3 signaling activation." (PMID 41573199, 2025). "Ginsenoside Rb1 improves insulin resistance and hepatic steatosis through the activation of the STAT3 pathway, promoting glycolytic enzyme GLUT2 and suppressing gluconeogenic enzyme PEPCK." (PMID 41304821, 2025). "LCN2 as an inflammatory marker can activate the STAT3 signaling pathway by its receptor 24p3R to exacerbate insulin resistance, nonalcoholic steatohepatitis and obesity." (PMID 40523992, 2025). "Increased activity of PPARα results in insulin resistance and defects in insulin signalling and STAT3 activity, reducing cardiac function." (PMID 41007642, 2025). "Three converging axes underpin risk: aromatase-mediated estrogen excess; insulin resistance with hyperinsulinemia activating PI3K–AKT–mTOR signaling; and adipokine-driven low-grade inflammation with downstream NF-κB/STAT3 activity." (PMID 41301707, 2025). "IL-6 contributes to insulin resistance through a complementary mechanism by activating the signal transducer and activator of transcription 3 (STAT3) pathway, which induces suppressor of cytokine signaling-3 (SOCS-3) expression." (PMID 41403736, 2025). "Aberrant activation of STAT3 represents a core molecular event linking inflammation and insulin resistance in GDM." (PMID 41460830, 2025). "This is seen in adipocytes where kynurenine, another known endogenous AhR ligand, triggers STAT3/IL-6, leading to insulin resistance and in cancer cells where this pathway leads to tumor resistance." (PMID 39684781, 2024). "Overexpression of STAT3 contributes to ovarian dysfunction and insulin resistance in mice, further exacerbating pathological changes." (PMID 39421869, 2024).
Insulin resistance (continued). "Taken together, these results suggest that the injection of IL-10-treated SVFs enhances Akt and STAT3 activation and attenuates insulin resistance in Leprdb/db mice." (PMID 39125659, 2024). "Inhibition of STAT3 can ameliorate insulin resistance, inflammation and oxidative stress in muscle and liver in T2DM model mouse." (PMID 38704482, 2024). "Signaltransducerandactivatoroftranscription3(STAT3) mediates insulin resistance in skeletal muscle, and mitochondrial gene expression and electron transport chain mechanisms in pancreatic beta cells." (PMID 39281650, 2024). "This suggests that the injection of IL-10-treated SVFs into the adipose tissue of diabetic mice suppresses gluconeogenic gene expression and insulin resistance through IL-10/STAT3 signaling in the liver." (PMID 39125659, 2024). "STAT3 is involved in cytokine- and nutrient-induced insulin resistance, and its phosphorylation contributes to skeletal muscle insulin resistance in T2D." (PMID 37680885, 2023). "The regulation of the JAK2/STAT3 pathway in the skeletal muscle of patients with type 2 DM is closely related to the occurrence of insulin resistance, and the phosphorylation of JAK2 and STAT3 can increase the incidence of glucose tolerance loss or DM." (PMID 35563546, 2022). "Animal studies have found that inhibiting the expression of STAT3 in obese rats can prevent the development of lipid-induced insulin resistance and reduce the incidence of diabetes." (PMID 36284987, 2022). "It is reported that HIF-1-alpha activates SCOS3 and following it hinders Janus kinase (JAK), which activates STAT3 and hence hinders the expression of adiponectin and promotes insulin resistance." (PMID 35956419, 2022). "As a result of the Stat3 pathway, involved in the cytokine and nutrient-mediated insulin resistance in skeletal muscles." (PMID 35414084, 2022). "The mechanism of IL-6-induced insulin resistance in the liver involves the activation of STAT3 and subsequent induction of the SOCS3 suppressor." (PMID 35052633, 2022). "furthermore, STAT3 acts as a link between obesity and diabetes by mediating lipid-induced insulin resistance." (PMID 35414084, 2022). "There are studies that have reported that Aβ induces hepatic insulin resistance by activating JAK2/STAT3/SOCS-1 signaling pathway and have implications on resolving insulin resistance and T2DM." (PMID 34991691, 2022). "Among these members, STAT3 has stood out, mainly for its involvement with insulin resistance and related pathologies, including GDM." (PMID 35052633, 2022). "In this connection, palmitic acid (as palmitate) treatment of L6 myotubes increased STAT3 phosphorylation and induced insulin resistance, which was prevented by silencing STAT3." (PMID 35889783, 2022). "Amyloid-β protein can lead to insulin resistance as well as the development of T2DM through the activation of the JAK2/STAT3/SOCS1 pathway." (PMID 34991691, 2022). "IL-6-activated STAT3 can induce insulin resistance through suppressors of cytokine signaling 3 (SOCS3); it can then inhibit the PI3K-AKT pathway, which reduces protein synthesis and increases myostatin transcription." (PMID 35846289, 2022). "Addition of SR1 significantly alleviated Kyn-induced insulin resistance as characterized by the increased p-AKTSer473 along with decreased STAT3, p-STAT3Tyr705 and reduced IL-6 secretion." (PMID 35715443, 2022). "Lycopene has been shown to have significant inhibitory effects on HFD-induced insulin resistance by preventing the expression and phosphorylation of STAT3 in a mouse model." (PMID 33808007, 2021). "The pro-inflammatory cytokine, IL-6, is a plausible mechanistic link between chronic inflammation and glucose intolerance/insulin resistance via the IL6/Jak2/Stat3 axis." (PMID 34943061, 2021). "Fbxo40, a muscle-specific E3 ubiquitin ligase targeting the IRS1 for degradation, is activated by Stat3 and contributes to muscular insulin resistance." (PMID 34943061, 2021).
Insulin resistance (continued). "Several studies have confirmed that STAT3 is a key regulatory factor of insulin resistance and has a close contact with the occurrence and development of type 2 diabetes." (PMID 33833859, 2021). "Katayama and colleagues described that miR-20b-5p promoted insulin resistance in skeletal muscle by inhibiting Akt expression and the activation of the signal transducer and activator of transcription 3 (STAT3)." (PMID 34440850, 2021). "It has been reported that the STAT3 pathway induces insulin resistance and the disruption of glucose metabolism in some cells and tissues, such as lung, kidney, and muscle." (PMID 35392577, 2021). "Meanwhile, activated PPARβ/δ prevents IL-6-induced insulin resistance by inhibiting the signal transducer and activator of transcription 3 pathway in adipocytes, which was enhanced in PPARβ/δ-null mice." (PMID 33083492, 2020). "In contrast, previous studies have shown that activating the IL6/STAT3 signaling pathway markedly ameliorates liver lipid metabolism, inflammation, and insulin resistance under HFD." (PMID 31949882, 2019). "Visfatin-induced inflammation and insulin resistance were regulated by JAK2/STAT3 and IKK/NF-κB signaling; together with AG490 or Bay 7082, visfatin significantly reduced mRNA levels of IL-6, TNF-α and IL-1β and rescued insulin signaling." (PMID 31396538, 2019). "In the liver, IL-6 induces insulin resistance by activating STAT3-suppressor of cytokine signalling 3 (SOCS3) pathway." (PMID 29558390, 2018). "PPARβ/δ activation prevents IL-6-induced insulin resistance by inhibiting the signal transducer and activator of transcription 3 (STAT3) pathway in adipocytes, whereas this pathway is over activated in PPARβ/δ-null mice compared to wild-type animals." (PMID 29558390, 2018). "The insulin resistance is one of the manifestations of aging and our data on changes in STAT3 expression with age are in good agreement with age-induced insulin resistance." (PMID 28783714, 2017). "We also used siRNA to determine the mechanisms and the crosstalk between IL-6 and TLR4 expression via STAT3 in the development of insulin resistance and glucose intolerance in the skeletal muscle." (PMID 28706484, 2017). "In hepatocytes, janus kinase 2/signal transducer and activator of transcription 3 pathway is the main pathway of its action, and leptin is involved in hepatic steatosis and insulin resistance through suppressor of cytokine signaling expression." (PMID 28081181, 2017). "Leptin and insulin resistance in the CNS can also result from overactivation of signal transducer and activator of transcription 3/suppressor of cytokine signaling 3 (STAT3/SOCS3), an intracellular pathway that is activated by leptin." (PMID 28592656, 2017). "The STAT3 signaling pathway participates in the development of insulin resistance in skeletal muscles and T2DM." (PMID 29228585, 2017). "STAT3 is a transcriptional factor that plays a role in the insulin resistance, and Casp2 is a proteolytic enzyme, whose activity is upregulated upon aging." (PMID 28783714, 2017). "Chronic activation of STAT3 has been reported to play a part in the development of insulin resistance by increasing the levels of SOCS1 and SOCS3 proteins." (PMID 28783714, 2017). "In the work of Serrano-Marco and colleagues, activation of PPARβ/δ with an agonist prevented induction of the transcription factor STAT3, which results in the prevention of insulin resistance in adipose tissue." (PMID 27519769, 2016). "Signal transducer and activator of transcription 3 (STAT3), a pivotal mediator in cardiac hypertrophy, was also found to be involved in PPARβ/δ-regulated insulin resistance in acute liver disease." (PMID 27519769, 2016). "Regarding the mechanism of how PPARδ ameliorates cardiac fibrosis, a previous study indicated that the PPARβ/δ agonist inhibited STAT3 activation and insulin resistance in human liver cells." (PMID 27519769, 2016).
Insulin resistance (continued). "A recent study about hepatic insulin resistance has shown that SHP inhibited STAT3 activation through protein-protein interactions with STAT3 in mouse models." (PMID 27127878, 2016). "Alexandrov showed that activation of PTEN and Stat3 mRNA translation leads to hepatic insulin resistance." (PMID 25048611, 2014). "Together, our findings indicate that miR-492 contributes to insulin resistance and endothelial dysfunction induced by high glucose, via directly downregulating resistin expression, and involving STAT3 phosphorylation, SOCS, and P-selectin activation." (PMID 24526524, 2014). "It has been reported that inactivation of STAT3 contributes significantly to the pathogenesis of insulin resistance." (PMID 23251458, 2012). "Thus, hepatitis viruses drive IFN-γ-mediated β-cell apoptosis through STAT3/IL-6/S100A8/A9 crosstalk, promoting insulin resistance and diabetes risk." (PMID 40918255, 2025). "In summary, CDD may improve ovarian function and insulin resistance in PCOS mouse by regulating the IL6/JAK2/STAT3/FOXO4 signaling pathway." (PMID 41573199, 2025). "As an alternative and complementary therapy, Cangfu Daotan Decoction may improve ovarian function and ameliorate insulin resistance in PCOS mice by modulating the IL6/JAK2/STAT3/FOXO4 signaling pathway." (PMID 41573199, 2025). "Given the importance of Stat3 in mediating Jak2-driven insulin resistance and inflammation in obese mice, we generated control (Lyz-Cre/Stat3+/+) mice and mice with macrophage cells lacking functional Stat3 alleles (Lyz-Cre/Stat3−/−)." (PMID 40801626, 2025). "CDD may improve ovarian function and insulin resistance in PCOS-IR mice by modulating the IL6/JAK2/STAT3/FOXO4 signaling pathway." (PMID 41573199, 2025). "The observed STAT3 activation in GDM placental cells treated with adipose tissue-derived EVs may contribute to insulin resistance and inflammation within the placenta, impacting placental function and nutrient transport to the fetus in GDM." (PMID 40369565, 2025). "The present study, taken together with the previous report, suggests that EPO could improve insulin resistance by activating the hepatic STAT3 pathway." (PMID 40943240, 2025). "The JAK2/STAT3 signaling pathway is involved in the development of insulin resistance in patients with T2DM, and its abnormal activation may damage pancreatic beta cells to reduce insulin synthesis." (PMID 40365304, 2025). "Key findings highlight the role of STAT3 in promoting insulin resistance and β-cell apoptosis, the impact of ER stress and NOX-mediated oxidative stress on metabolic dysfunction, and the influence of epigenetic changes such as DNA methylation and histone acetylation on glucose homeostasis." (PMID 40918255, 2025). "In this context, the changes in LIFR expression could be related to susceptibility to NAFLD and insulin resistance in patients with LADA, and the LIFR/JAK/STAT3 inflammatory pathway enhances adipocyte lipolysis." (PMID 39337639, 2024). "The increased expression of SOCS3 may induce the development of insulin resistance by inhibiting the JAK/STAT3 signaling pathway." (PMID 39596180, 2024). "IL-6 exacerbates insulin resistance by activating STAT-3 in hepatocytes." (PMID 37996879, 2023). "Regarding the mechanism of higher blood glucose levels and insulin resistance in Il18−/− mice, the phosphorylation of signal transducer and activator of transcription 3 (STAT3) was impaired in the liver and was recovered by the administration of recombinant-IL18 (rIL18)." (PMID 38139000, 2023). "Therefore, in obese subjects, curcumin can reduce inflammation and insulin resistance by inhibiting activation of signal transducers and activation of transcription 3 (STAT3) in human adipocytes." (PMID 37375898, 2023). "Moreover, it facilitates the development of insulin resistance and triggers the phosphorylation of signal transducer and activator of transcription 3 (STAT3), thereby further amplifying the inflammatory response observed in obese mice." (PMID 38068762, 2023).